EGFR (epidermal growth factor receptor)
Diseases named in the same sentence as EGFR in open-access papers (continued):
Sharing a sentence is not in itself a finding about the gene and the disease.
cancer (continued). "Elaic acid, a major long-chain trans-fatty acid, has been shown to transform cancer by altering specific G protein and epidermal growth factor receptor signaling pathways." (PMID 37781114, 2023). "Chemotherapeutic resistance often occurs after EGFR mutagenesis-related cancer patients take targeted-therapy medication for a median time of 12 months." (PMID 37333807, 2023). "CUR changed the expression of EGFR, microRNAs and autophagy in cancer stem cells and influences the expression of different genes in the cancer cells, such as NF‐kB, STAT‐3 and AP‐1, as well as protein kinases, including MAPK and enzymes such as COX and LOX." (PMID 37697969, 2023). "The left, middle and right subfigures are WSIs, cancer detection, and EGFR prediction heatmaps, respectively." (PMID 37407963, 2023). "In the KEGG pathway analysis, EGFR tyrosine kinase inhibitor resistance (hsa01521), Central carbon metabolism in cancer (hsa05230), and PI3K/AKT signaling pathway (hsa04151) became the top three significantly enriched." (PMID 37379130, 2023). "A typical regulator of angiogenesis, which share common downstream signaling with EGFR pathway in cancer cells." (PMID 37800802, 2023). "Epidermal growth factor receptor (EGFR) is a type of membrane-bound tyrosine kinase receptor which addicted to the treatment of cancer." (PMID 37501139, 2023). "Taken together, these results highlight a novel glycosylation-dependent mechanism by which cancer cells hijack EGFR signaling to enhance tumor-promoting signaling pathways." (PMID 37660914, 2023). "The present work elucidates a functional mechanism that links calcium homeostasis to EGFR signaling in cancer." (PMID 37442828, 2023). "PET1 binds selectively to EGFR in cancer cells and inhibits the ability of the ligand EGF to activate cell migration." (PMID 37315787, 2023). "BDNF and EGF act on downstream receptors [tropomyosin receptor kinase b (TrkB) and EGFR] on the surface of cancer cells and activate pathways ensuring cancer cell invasiveness." (PMID 37056723, 2023). "The overexpression of EGFR is involved in varied types of cancer, such as breast, ovarian, prostate, and colon cancers, by stimulating neoplastic cell proliferation, metastasis, angiogenesis, and invasiveness." (PMID 36678593, 2023). "NETs are involved in cancer cell invasion and metastasis by inducing epithelial–mesenchymal cell differentiation and transformation through the activation of the EGFR/ERK pathway." (PMID 37626816, 2023). "MiR-708 interferes with the GTPase Ras-proximity-1B (Rap1B) protein, whose activity has been shown to specifically promote epidermal growth factor receptor (EGFR)-dependent cancer cell migration." (PMID 37189400, 2023). "To date, it is known that EGFR endocytosis and cytoprotective autophagy triggered by TKI treatment serve as bypass drug-resistant mechanisms in cancer cells; however, the underlying mechanism remains a mystery." (PMID 37495186, 2023). "The epidermal growth factor receptor (EGFR) plays an important role in many cancers through downstream signaling via the MAPK pathway (see Section 3.3.4) as well as the PI3K/Akt/mTOR pathway." (PMID 37444422, 2023). "Several monoclonal antibodies have already been applied in the imaging and treating of EGFR-positive cancers, including cetuximab, panitumumab, nimotuzumab, etc., targeting the extracellular domain of EGFR." (PMID 38067344, 2023). "EGFR is an attractive and effective target on its own, provided it has a recognized role in cancer cell subsistence and spread." (PMID 38090376, 2023). "These phage-derived ligands have exhibited potential in the development of targeted therapies for EGFR-positive cancers." (PMID 37243023, 2023). "In this review, we describe the interplay between COX2/mPGES1/PGE2 and EGFR in cancer, and new therapeutic strategies that target this signaling pathway, to outline the importance of the modulation of the inflammatory process in cancer fighting." (PMID 37190301, 2023).
cancer (continued). "To functionally characterize the importance of EGFR in mediating the cancer stemness properties directed by SPINK1, we treated HCC cells with recombinant SPINK1, in the absence or presence of EGFR knockdown or FDA-approved EGFR inhibitor, Erlotinib." (PMID 38030644, 2023). "There has been an ever-growing interest in the use of epidermal growth factor receptor (EGFR) inhibitors in various cancers in the recent years." (PMID 37310466, 2023). "In vitro studies with mucoepidermoid cancer models positive for CRTC1-MAML2-positive present sensitivity to EGFR inhibitors, such as erlotinib, gefitinib, or cetuximab, that in the future can be an attractive therapeutic option." (PMID 37439929, 2023). "By increasing the time from the last administration of anti-EGFR drugs, a progressive reduction in resistant cancer cell clones was proposed." (PMID 37046778, 2023). "The epidermal growth factor receptor (EGFR) is the prototype of tyrosine kinase receptors which contributes to human cancer development and progression." (PMID 37114127, 2023). "Elevated levels of EREG appear to be a potential predictive biomarker of anti-EGFR therapies in several cancer types including HNSCC." (PMID 36899869, 2023). "EGFR signaling cascade is a key regulator in cell proliferation, differentiation, survival and cancer transformation." (PMID 37511133, 2023). "EGFR is a rational target for cancer therapy because it is commonly expressed at a high level in a variety of solid tumors and it has been implicated in the control of cell survival, proliferation, metastasis, and angiogenesis." (PMID 36817123, 2023). "The signaling network downstream of EGFR is one of the most frequently deregulated in cancer, and due to the multiple facets of EGFR cell trafficking, the role of sorting proteins such as Sortilin is of increasing interest." (PMID 37576898, 2023). "EGFR is a useful biomarker for a variety of cancers, because it is expressed at high levels relative to normal tissues." (PMID 37419997, 2023). "At the nucleic acid level, the role of EGFR in the occurrence and development of cancer is closely related to some long‐chain noncoding RNAs (lncRNAs)." (PMID 38107059, 2023). "In this review, we describe and compare technologies for the targeted inhibition and targeted degradation of the epidermal growth factor receptor (EGFR), one of the major proteins responsible for the onset and progression of many types of cancer." (PMID 37754201, 2023). "For example, our group showed that nitrogen-containing bisphosphonates can directly inhibit the growth of EGFR-driven cancer cells, making it possible to potentially repurpose them to treat lung, breast, gastrointestinal, head and neck, and other cancers." (PMID 36656634, 2023). "EGFR signaling is a part of a complex network that has been the target of effective cancer therapies." (PMID 37716963, 2023). "Three generations of tyrosine kinase inhibitors (TKIs) for the EGFR were developed for the treatment of cancer patients, and the respective therapeutic molecules were grouped according to their structure or the target sites in the receptors." (PMID 37754201, 2023). "EGFR signaling is crucial for cell multiplication and also contributes towards cancer progression, angiogenesis, metastasis, motility, adhesion, invasion, and inhibition of apoptosis." (PMID 38090376, 2023). "Collectively, these data suggest that the co-occurrence of CBX3 and EGFR gene amplification is a frequent event in cancer that ultimately leads to an increased expression of both genes." (PMID 37633946, 2023). "The roles of EGF and EGFR in human cancer have been extensively reviewed with an emphasis on their clinical significance including consideration of multiple inhibitory strategies targeting EGFR activity for cancer therapeutics." (PMID 36979595, 2023). "When EGFR is inhibited, cancer cells show a higher sensitivity to ionizing radiation in preclinical studies on HNSCC." (PMID 37372319, 2023).
cancer (continued). "Necitumumab in combination with osimertinib is being tested in a phase II platform study (ORCHARD) for patients with EGFR-mutant NSCLC who had cancer progression on osimertinib." (PMID 37296863, 2023). "Some of the most well-characterized RTKs implicated in cancer include the “HER family”, i.e., epidermal growth factor receptor (EGFR), ErbB2 (neu, HER2), ErbB3 (HER3) and ErbB4 (HER4), as well as VEGF/VEGFR, which is discussed in the following paragraphs." (PMID 38136430, 2023). "One of the well-known activators of macropinocytosis is EGFR, which is also one of the most frequently activated receptor tyrosine kinases in cancer." (PMID 37420029, 2023). "Epidermal growth factor receptor (EGFR) plays an important role in the occurrence and development of cancer." (PMID 37481519, 2023). "The epidermal growth factor receptor (EGFR) plays important roles in cancer progression and is one of the major drug targets for targeted cancer therapy." (PMID 36739948, 2023). "HGFI was fused with the GE11 peptide to target the EGFR, which is highly expressed in some types of cancers." (PMID 37237914, 2023). "In contrast, the combination of EGFR mAbs and ICIs in various cancer types (including CRC, HNSCC, and NSCLC) demonstrated promising clinical efficacy (improved median PFS) without significant adverse effects." (PMID 37631380, 2023). "Most patients treated with EGFR-TKIs develop skin toxicity, which can affect quality of life and lead to discontinuation of cancer treatment." (PMID 37089959, 2023). "One mechanism for this observed intrinsic resistance in other cancer types is the activation of the MAPK pathway by EGFR." (PMID 38136350, 2023). "Several studies reported that the EGFR signaling pathway regulated cancer metastasis and MMP expression." (PMID 36770659, 2023). "c-erbB proto-oncogene encodes the EGFR, and the gene neu encodes for HER2 which has been found in various cancers." (PMID 38090376, 2023). "We present a case study on the BP with ID BIOMD0000000394, which refers to the Epidermal Growth Factor Receptor (EGFR) signaling pathway, a well-studied BP whose alterations have been linked to cancer." (PMID 37951586, 2023). "•Cannabinoids & Terpenes derived from Cannabis sativa L. screened in silico for targeting cancer via inhibiting the EGFR-TKD enzyme." (PMID 37128337, 2023). "EGFR mutations were associated with reduced TMB in LUAD and increased TMB in nine other cancer types." (PMID 36911742, 2023). "Various mAbs targeting the extracellular region of the EGFR were developed and approved by many laboratories to inhibit receptor activity in cancer." (PMID 37754201, 2023). "Targeting abnormal EGFR is one of the major signal blockade strategies to treat patients with several cancers including OSCC." (PMID 37341071, 2023). "Currently, osimertinib is approved by major regulatory agencies for the treatment of T790M-positive cancers, which progressed after treatment with first- or second-generation EGFR TKIs." (PMID 38201251, 2023). "The research focused on exploring the mechanisms of EGFR inhibitor resistance and the impact of cancer stroma interactions between fibroblasts and drug-sensitive or drug-resistant cancer cells, which are not yet well understood." (PMID 37533100, 2023). "Overexpression of EGFR has been observed in many cancer types, which affects the cell cycle by inducing these mechanisms." (PMID 37759771, 2023). "This provides an opportunity for redirecting EGFR mutants to the lysosomal degradation route as an anti-cancer strategy." (PMID 37821451, 2023). "EGFR is a transmembrane receptor that is overexpressed in many types of cancer and is involved in cell proliferation, migration, invasion, and angiogenesis." (PMID 37240450, 2023). "Targeting the epidermal growth factor receptor (EGFR) has become very important in cancer research and therapy due to its overexpression in many different types of solid tumors and its association with metastasis and poor prognosis." (PMID 36977072, 2023).
cancer (continued). "Increased EGFR and STAT5 are observed in malignant cancers, and upregulation of their targets is often associated with cancer progression." (PMID 36671501, 2023). "These anti‐EGFR‐resistant cancer clones decay over time after the interruption of EGFR inhibitor treatment with half‐life of approximately 4 months." (PMID 36880426, 2023). "Cetuximab is a monoclonal antibody that binds to EGFR, approved as a first-line treatment for many cancers." (PMID 37627119, 2023). "Gefitinib (also named Iressa) is a potential anti-cancer drug for clinical cancer therapy, and it is known as an epidermal growth factor receptor (EGFR) tyrosine kinase inhibitor (TKI)." (PMID 36768961, 2023). "They serve as impermeable micro-reservoir carriers that enable effective packing of a variety of various medicines, proteins, or nucleic acids; (c) targeting moiety, an anti-EGFR bispecific antibody directs the EDVs to cancer cells that express EGFR." (PMID 36821071, 2023). "Clinically, GEM remains one of the first-line therapeutic agents for cancer patients who have developed resistance to EGFR-TKI." (PMID 37705111, 2023). "EGFR2 deletions 755–759 were found to be homologous to EGFR exon 19 deletions that produced GEF-sensitive NSCLC, and consequently, this indicates that HER2 mutations would also influence cancer behaviour and outcome." (PMID 38090376, 2023). "hBD-3 enhances cancer metastasis, and this effect can be blocked by inhibiting EGFR or neutralizing TLR4 in SCC-25 cells." (PMID 36980171, 2023). "The drug response profiles observed in all three FMOC02 PDCs were remarkably similar and showed continued dependency of cancer cells on the ERBB2/EGFR and RAS/ERK signalling." (PMID 36476658, 2023). "Overexpression of EGFR in cancers is often correlated with poor prognosis, invasiveness, metastasis, and drug resistance." (PMID 38137520, 2023). "The authors develop a multiplexed imaging system to analyze the immunophenotype of cells by detecting three commonly overexpressed cancer cell receptors—EGFR, IGF-1R, and HER-2." (PMID 37998152, 2023). "Previously, sialylation has been reported to suppress EGFR activation and increase cancer cell sensitivity to Tyrosine Kinase Inhibitors (TKIs)." (PMID 37687086, 2023). "TIS derived from cancer cells treated with targeted inhibitors of EGFR, BRAF, or HER2 signaling unanimously led to an elevated secretome fucosylation." (PMID 36961502, 2023). "Several EGFR inhibitors have been demonstrated to be highly effective in cancer patients with EGFR mutants." (PMID 36875137, 2023). "We conducted an oncology protein array to measure 84 major cancer-related proteins in both A549 cells and A549 EVs and found that EpCAM, EGFR, Dkk-1, Galectine-3, Endostatin, E-Cadherin, FGF basic, Vimentin, and progranulin are the top nine hits." (PMID 36834913, 2023). "One interesting example is that DMEA identified HMGCR inhibitors as potentially toxic to cancer cells with intrinsic resistance to EGFR inhibitors." (PMID 37226094, 2023). "On the other hand, C_42 derived from natural sources can be considered a potential inhibitor of triple mutant EGFR in cancer treatment and an alternative to chemically synthesized." (PMID 37264083, 2023). "The epidermal growth factor (EGF) is one of the most critical ligands of the EGF receptor (EGFR), a well-known oncogene frequently overexpressed in cancerous cells and an important therapeutic target in cancer." (PMID 37241784, 2023). "Evaluation of proteomic data (RPPA) from TCGA profiling evidenced a significant correlation between Sorcin mRNA expression and EGFR pY1068 in various cancer types." (PMID 37442828, 2023). "A number of other RTKs, such as insulin/IGF receptors and EGFR, activate Akt in other cellular contexts such as growth and proliferation of various stem cells and mammalian cancer cells." (PMID 36647607, 2023).
cancer (continued). "The results indicated that the pathways in the cancer signaling pathway (with 30 associated genes), PI3K/Akt signaling pathway (with 20 associated genes) and EGFR tyrosinase inhibition resistance (with 16 associated genes) were the main signaling pathways." (PMID 36768602, 2023). "In particular, the significance of EGFR signaling cascade in cancer progression has been drawing substantial attention; the EGF stimulation system for growth regulation is implicated in both normal and neoplastic cell proliferation." (PMID 36979595, 2023). "Our data on cancer cell death during the degradation of the EGFR by chemical compounds are also of interest for the development of other transmembrane proteins’ degradation." (PMID 37754201, 2023). "For instance, the epidermal growth factor receptor (EGFR) is upregulated in several types of cancer." (PMID 37107691, 2023). "The potentially useful new therapeutic anti-cancer drugs that block EGFR and/or HER-2 kinase activity upon ATP attachment to the receptor." (PMID 37291635, 2023). "Previous studies demonstrated that RHOV functions as an oncogene in LUAD, promoting cancer cell growth, metastasis, and resistance to epidermal growth factor receptor (EGFR)‐tyrosine kinase inhibitor therapies." (PMID 37596964, 2023). "Combined treatment with THZ531 and inhibitors of pathways regulated by these cancer relevant genes (EGFR, RPTOR, ATRIP) exerted synergic effects on HGSOC PDO viability." (PMID 37202753, 2023). "There has been growing interest in the use of epidermal growth factor receptor inhibitors in various cancers." (PMID 37310466, 2023). "In keratinocytes and intestinal epithelial cells, as well as in cancer cells, it is known that EGFR can modulate the desmosomal structure, assembly, and signaling and vice versa." (PMID 36795511, 2023). "Compound I was reported to have potent anticancer activity against four cancer cell lines, as well as promising EGFR inhibitory activity." (PMID 36770936, 2023). "Taking into account all the benefits of immunoliposomes in cancer treatment, the objective of this study is to develop, using a factorial design approach, pH-sensitive, anti-EGFR immunoliposomes for DTX delivery." (PMID 36986777, 2023). "Mechanistic evidence showed that miR-7-5p can inhibit the proliferation of cancer cells through regulating the expression of EGFR." (PMID 37114127, 2023). "Here, we have utilized the BAR domain of Sorting Nexin 1 to create a peptide-based therapeutic (cSNX1.3) that promotes cell death in EGFR-expressing cancer." (PMID 36253541, 2023). "It is widely recognized that radiation can increase tyrosine phosphorylation of EGFR signaling, and its phosphorylation promotes postirradiation repopulation of cancer cells." (PMID 37802999, 2023). "EGFR inhibition is one of the main strategies of treatment in cancer with abnormal activation of this tyrosine kinase receptor such as non-small lung cancer." (PMID 37511133, 2023). "We further investigated the direct comparison of cellular internalization and cytotoxic effects of NmAb-functionalized AuNPs and NmAb themselves with different levels of EGFR-expressing cancer cells for skin (A431) and lung (A549)." (PMID 37623652, 2023). "Currently, there are five first-generation (gefitinib, erlotinib, lapatinib, vandetanib, and icotinib) and two second-generation (afatinib and dacomitinib) quinazoline-based EGFR inhibitors approved for the treatment of various types of cancers." (PMID 37111291, 2023). "Previous studies using molecular markers- EGFR, Ki67 had an accuracy of 70% for delineation of cancer and pre-cancer lesions." (PMID 37747904, 2023). "Of note many other mechanisms are involved in the anti-cancer effects of biguanides, some of them more related to the specific cancer type, like, for example, the interaction of proguanil with EGFR in glioblastoma cells." (PMID 38146457, 2023).